ADGRG4 (adhesion G protein-coupled receptor G4)
Description:
Orphan adhesion G protein-coupled receptor (aGPCR) (By similarity). Ligand binding causes a conformation change that triggers signaling via guanine nucleotide-binding proteins (G proteins) and modulates the activity of downstream effectors, such as adenylate cyclase (By similarity). ADGRG4 is coupled to G(s) G proteins and mediates activation of adenylate cyclase activity. May be act as sensor of mechanical forces.
Synonyms: GPR112; RP1-299I16; PGR17
Tractability: Antibody: UniProt predicts a signal peptide or a membrane-spanning region; its Gene Ontology location is reachable by antibodies, with medium confidence. PROTAC: ubiquitination databases record sites on it.
Gene: Protein-coding gene on chromosome X (136,300,963 to 136,416,890, forward strand). Ensembl gene ENSG00000156920.
Subcellular location: Membrane
Gene Ontology:
Molecular function: G protein-coupled receptor activity; transmembrane signaling receptor activity
Biological process: adenylate cyclase-activating G protein-coupled receptor signaling pathway; G protein-coupled receptor signaling pathway; cell surface receptor signaling pathway
Cellular component: membrane; plasma membrane
Homologues: Orthologues: chimpanzee ADGRG4 (99% identical), macaque ADGRG4 (93% identical), rabbit ADGRG4 (62% identical), dog ADGRG4 (60% identical), mouse Adgrg4 (59% identical). Paralogues in human: ADGRG6 (12% identical), ADGRG2 (11% identical), ADGRF5 (7% identical), ADGRL3 (6% identical), ADGRL2 (6% identical), ADGRL1 (6% identical), ADGRB1 (6% identical), ADGRB2 (6% identical), ADGRE2 (5% identical), ADGRA3 (5% identical), ADGRA2 (5% identical), ADGRB3 (5% identical), and 30 more.
Diseases named in the same sentence as ADGRG4 in open-access papers:
ADGRG4 is named in the same sentence as 10 diseases in open-access papers, as found by Europe PMC text mining. Sharing a sentence is not in itself a finding about the gene and the disease.
ADGRG4 shares sentences with these, for which no sentence is quoted: cancer (4 papers); breast carcinoma (1); colorectal cancer (1); congenital heart defects (1); endometriosis (1); glioma (1); melanoma (1); neurodevelopmental disorder (1); neuroendocrine carcinoma (1); tumor (1).